NLRP3 (NLR family pyrin domain containing 3)
Diseases named in the same sentence as NLRP3 in open-access papers (continued):
Sharing a sentence is not in itself a finding about the gene and the disease.
cardiac hypertrophy (69 papers, 2016 to 2026). "Yue and colleagues discovered that pyroptosis mediated by NLRP3 worsens myocardial hypertrophy, fibrosis, and the dysfunction caused by pressure overload in mice." (PMID 41150514, 2025). "Consistently, immunoblotting further demonstrated that NLRP3 deletion attenuated the aggravation of cardiac hypertrophy and fibrosis caused by TXNIP overexpression." (PMID 39604027, 2024). "The data indicate that the anti-pyroptosis and cardiac hypertrophy effects of MYOF are associated with NLRP3 inflammatory signaling." (PMID 39553724, 2024). "Conversely, inhibiting the NLRP3 inflammasome has demonstrated a protective effect against atrial fibrillation caused by cardiovascular aging, as well as overload-induced cardiac hypertrophy." (PMID 38338718, 2024). "Overactivation of NLRP3 inflammasome has been linked to myocardial fibrosis, hypertrophy, and cardiac dysfunction." (PMID 37958859, 2023). "The decrease in the level of ROS causes the NLRP3 inflammasome to fail to assemble and activate the caspase-1 signaling pathway, thereby inhibiting pyroptosis and cardiac hypertrophy." (PMID 35647057, 2022). "NLRP3 deficiency accelerated cardiac hypertrophy, fibrosis, and inflammation responses with deteriorating cardiac dysfunction." (PMID 35990977, 2022). "The present study demonstrated that Nlrp3 inflammasome activation was involved in Ang II-induced cardiac fibrosis and hypertrophy, ultimately causing cardiomyopathy." (PMID 33628380, 2021). "In the present study, we have used a transverse aortic constriction (TAC) mouse model to demonstrate that NLRP3 inflammasome activation is associated with the progression of heart hypertrophy." (PMID 34567409, 2021). "However, the precise role and underlying molecular mechanisms of NLRP3 inflammasome in cardiac hypertrophy remain ambiguous." (PMID 38172711, 2024). "Therefore, we think that cardiac mitophagy dysfunction induced by pressure overload activates NLRP3 inflammasome to cause cardiac hypertrophy." (PMID 38782946, 2024). "In addition, NLRP3 inflammatory vesicles have been shown to be closely associated with cardiac inflammation and myocardial hypertrophy." (PMID 38402404, 2024). "NLRP3 deficiency accelerates pressure overload-induced cardiac hypertrophy and fibrosis." (PMID 35287557, 2022). "However, NLRP3−/− homozygous mutation accelerated cardiac hypertrophy, fibrosis, and myocardial inflammation in pressure overload-induced cardiac remodeling in mice." (PMID 36320147, 2022). "Herpud1 inhibition has recently been associated with induced pathological cardiac hypertrophy, which could explain the reduced hypertrophy observed in NLRP3 −/− mice." (PMID 31625260, 2020). "In addition, NLRP3 deficiency accelerates cardiac hypertrophy, fibrosis, as well as inflammation responses induced by pressure overload in a cardiac remodeling mouse model." (PMID 31354731, 2019). "Additionally, our results suggest that miR-26a-5p may activate autophagy, leading to the activation of the NLRP3 inflammasome and subsequently causing an increase in cardiac hypertrophy." (PMID 38172711, 2024). "Finally, the molecular mechanism of miR-26a-5p regulating autophagy leading to NLRP3 inflammasome activation was further explored, and the potential clinical value of miR-26a-5p molecule as a diagnostic and therapeutic target for cardiac hypertrophy was elucidated." (PMID 38172711, 2024). "The therapeutic intervention of NLRP3 gene silencing demonstrated significant improvements in cardiac hypertrophy, pyroptosis, fibrosis, and cardiac function." (PMID 40242439, 2025). "Knockdown of lncMEG3 attenuates inflammation and NLRP3 inflammasome-mediated pyroptosis, thereby ameliorating myocardial hypertrophy, cardiac fibrosis, and cardiac dsyfunction through modulation of the miR-223/NLRP3 pathway." (PMID 40242439, 2025). "Regulation of the NLRP3 inflammasome can mitigate cardiac hypertrophy, enhance diastolic and systolic function, and inhibit the progression of HF." (PMID 41194915, 2025).
cardiac hypertrophy (continued). "Low PRMT5 expression triggered the activation of the E2F-1/NF-κB signaling pathway, leading to the activation of the NLRP3 inflammasome that promotes maladaptive cardiac hypertrophy induced by transverse aortic constriction (TAC) or Ang II." (PMID 39925805, 2025). "Transfection of cardiomyocytes with si-NLRP3 or the caspase-1 inhibitor VX-765 limited SiNP-induced pathological cardiac hypertrophy." (PMID 39925805, 2025). "Activation of the NLRP3 inflammasome has been shown to induce myocardial hypertrophy under pressure overload." (PMID 40076760, 2025). "In the context of cardiac remodeling, the activation of the NLRP3 inflammasome promotes not only cardiac inflammation and fibrosis but also aggravates pathological myocardial hypertrophy, consequently exacerbating symptoms of HF." (PMID 39925805, 2025). "In mouse models, aerobic exercise has been found to significantly inhibit the activation of the NLRP3/caspase-1/IL-1β signaling pathway, resulting in reduced myocardial hypertrophy and fibrosis." (PMID 41194915, 2025). "NLRP3 is involved in pressure overload-induced cardiac hypertrophy by mechanisms such as muscle LIM protein S-nitrosylation to activate IL-1β signaling and amplify myocardial dysfunction." (PMID 40564905, 2025). "This upregulation primarily facilitated the interaction between TLR3 and receptor-interacting protein kinase 3 (RIP3), thus initiating activation of the NF-κB/NLRP3 inflammasome pathway, ultimately fostering the progression of myocardial hypertrophy." (PMID 39925805, 2025). "The activation of the NLRP3 inflammasome not only enhances myocardial inflammatory responses but also promotes the development of cardiac hypertrophy and fibrosis, creating a pro-arrhythmic environment." (PMID 39925805, 2025). "The increase in pyroptosis in myocardial hypertrophy was accompanied by enhanced regulation of NLRP3, caspase-1, ASC, and GSDMD." (PMID 39553724, 2024). "The present study aimed to examine the impact of MYOF on pressure overload-induced myocardial hypertrophy and its influence on NLRP3-mediated pyroptosis in an in vivo model of myocardial hypertrophy." (PMID 39553724, 2024). "Metformin can promote autophagy throughthe mTOR signaling pathway, inhibit the activation of NLRP3 inflammasome,regulate cell pyroptosis, and alleviate cardiac hypertrophy." (PMID 39484135, 2024). "Cardiomyocytes were treated with 200μM PE to induce cardiac hypertrophy and intervened with 10mM NLRP3 inhibitor INF39." (PMID 38172711, 2024). "Activation of the NLRP3 inflammasome has been identified as key driver of cardiac hypertrophy in response to pressure overload." (PMID 38791409, 2024). "We found that compared to 12-HETE‒treated TAC-operated WT mice, 12-HETE‒treated TAC-operated Nlrp3 KO mice had reduced cardiac cell death and reduced cardiac hypertrophy." (PMID 39327446, 2024). "Studies employing pharmacologic blockade or ribonucleic acid (RNA) interference targeting NLRP3, as well as the inhibition of IL-1β with neutralizing antibodies, have demonstrated mitigated pressure overload-induced myocardial hypertrophy." (PMID 38791409, 2024). "The Studies also reported that elevated mRNA of NLRP3 and enhanced cleavage of caspase-1 were observed along with cardiac hypertrophy and ventricular dilatation in calcineurin transgene (CNTg) mice, an established mouse model for chronic heart failure." (PMID 38750444, 2024). "This suggests that pharmacological or genetic inhibition of NLRP3 can effectively reduce cardiac hypertrophy." (PMID 39553724, 2024). "ATP has been characterized as an activator of the inflammasomes, which in turn triggers inflammation in the heart and leads to cardiac hypertrophy through the activation of NLRP3." (PMID 38338718, 2024). "NLRP3 KO mice resulted in a significant decrease in IL-1β production, along with reduced cardiac hypertrophy and impaired contractile function under pressure overload conditions." (PMID 39594530, 2024).
cardiac hypertrophy (continued). "This complex activation subsequently triggers NLRP3 inflammasome activation and IL-1β production, fostering myocardial hypertrophy." (PMID 38791409, 2024). "Overall, Rg3 combats Ang II-induced myocardial hypertrophy by deactivating the NLRP3 inflammasome and oxidative stress via the SIRT1/NF-κB pathway." (PMID 39108942, 2024). "CRID3 can target and inhibit the release of the NLRP3 inflammasome, reduce pyroptosis, attenuate pathological myocardial hypertrophy, and improve overall cardiac function." (PMID 39553724, 2024). "In conclusion, semaglutide ameliorates the cardiac hypertrophy by improving cardiac mitophagy to suppress the activation of NLRP3 inflammasome." (PMID 38782946, 2024). "We then performed TAC surgery on Nlrp3 KO and WT mice and measured heart mass and cardiac Evans blue uptake in order to examine cardiac hypertrophy and cardiac cell death, respectively." (PMID 39327446, 2024). "Studies have shown that in a TAC-induced myocardial hypertrophy model, the NLRP3 inflammasome can be alleviated by regulating the NF- κB signaling pathway to alleviate myocardial hypertrophy." (PMID 39553724, 2024). "LncRNA GAS5, as previously noted, can enhance heart function and even cure signs of myocardial hypertrophy in DCM mice by suppressing NLRP3 activation." (PMID 37396588, 2023). "NLRP3 inflammasome activation by TMAO triggers cardiac hypertrophy and fibrosis through the suppressor of mothers against decapentaplegic 3 (Smad 3) signaling pathway." (PMID 37111261, 2023). "Pharmacologic blockade or RNA interference of NLRP3 and inhibition of IL-1β can reduce pressure overload-induced myocardial hypertrophy." (PMID 35509275, 2022). "The NLRP3 inflammasome is activated and increases caspase-1 and IL-1β expression in a rat myocardial hypertrophy model developed by aortic transverse contraction and in human cardiomyocytes treated with angiotensin II." (PMID 36111168, 2022). "Elevated levels of NLRP3 mRNA in cardiac hypertrophy, inflammatory response, and ventricular dilatation were observed in mouse models." (PMID 35464402, 2022). "Pyrroloquinoline quinone inhibited ROS and NF-κB activation inhibited NLRP3 inflammasome and Caspase-1, IL-1β and IL-18 expression, and improved myocardial hypertrophy and cardiac fibrosis." (PMID 35509275, 2022). "The pharmacological inhibition of NLRP3 or NLRP3 knockout reduced myocardial inflammation, fibrosis, myocardial hypertrophy, and cardiac dysfunction." (PMID 35721118, 2022). "Taken together, irisin mitigated pressure overload-induced pyroptosis, as well as cardiac hypertrophy and fibrosis, by targeting the NLRP3 inflammasome." (PMID 33723236, 2021). "NOD-like receptor protein 3 (NLRP3) and the pyroptotic cascade play a critical role in cardiac hypertrophy and inflammation." (PMID 33723236, 2021). "To this end, we established in vivo and in vitro models of cardiac hypertrophy and analyzed the effects of irisin on pressure overload-stimulated cardiac hypertrophy and NLRP3-mediated pyroptosis." (PMID 33723236, 2021). "Pharmacologic blockade or RNA interference of NLRP3 and inhibition of IL-1β with neutralizing antibody reduced pressure overload-induced myocardial hypertrophy." (PMID 34776995, 2021). "Previous investigations have shown that the IL-1β and NLRP3 inflammasomes are involved in cardiac hypertrophy." (PMID 34168567, 2021). "We established a direct association between pyroptosis and cardiac hypertrophy and found that pharmacological or genetic inhibition of NLRP3 attenuated cardiac hypertrophy." (PMID 33723236, 2021). "One investigation showed that IL-1β and the NLRP3 inflammasome play an important role in pressure overload-induced cardiac hypertrophy in mice." (PMID 34168567, 2021). "In the present study, we have demonstrated that NLRP3 inflammasome activation, along with accompanying secretion of cytokines, contributed to the progression of cardiac hypertrophy in a TAC mouse model." (PMID 34567409, 2021).
cardiac hypertrophy (continued). "In this study, we induced cardiac hypertrophy in a mouse model via aortic constriction (TAC) to further explore the pathological role of NLRP3 inflammasome-mediated pyroptosis and the potential therapeutic effects of irisin." (PMID 33723236, 2021). "Enhanced inflammation via activation of the nucleotide-binding and leucine-rich repeat pyrin domains protein 3 (NLRP3) inflammasome and concomitant secretion of cytokines contributes to the progression of cardiac hypertrophy." (PMID 34943043, 2021). "Our findings indicated that NLRP3/caspase-1-dependent pyroptosis has a pathological role in myocardial hypertrophy." (PMID 33723236, 2021). "To summarize, pyroptosis is a pathological factor in cardiac hypertrophy, and irisin is a promising therapeutic agent that inhibits NLRP3-mediated pyroptosis of cardiomyocytes." (PMID 33723236, 2021). "The current study establishes the presence of excessive NLRP3 inflammasome activation in TAC-induced cardiac hypertrophy and dysfunction." (PMID 34567409, 2021). "Liraglutide significantly attenuated cardiac hypertrophy, pathological changes, inflammation, pyroptosis, and NLRP3 inflammasome activation, accompanied by increased Sirt1 and AMPK activation." (PMID 35096293, 2021). "Previous investigators have demonstrated that prorenin and PRR are involved in the pathogenesis of renal and cardiac hypertrophy, accompanied by local oxidative stress, inflammation, and NLRP3-IL-1β-related signals." (PMID 32242284, 2020). "Collectively, these findings suggest that presence of the Nlrp3 gene is not required for Western diet-induced AT inflammation and/or glucose intolerance; yet Nlrp3 appears to play a role in potentiating arterial stiffening, cardiac hypertrophy and fibrosis." (PMID 27583382, 2016). "Therefore, they exhibited upregulation of S100A8/A9, which led to exacerbation of inflammation, cardiac hypertrophy and fibrosis via activation of the NF-κB/NLRP3, AKT/Calcineurin A and TGF-β/Smad2 signaling pathways." (PMID 40860162, 2025). "For example, free fatty acid-induced mitochondrial damage and the consequent release of mtDNA can activate cGAS–STING, thereby promoting pyroptosis and pro-inflammatory responses through an NLRP3 inflammasome-dependent mechanism and ultimately contributing to myocardial hypertrophy in DCM." (PMID 41008530, 2025). "In addition, they showed that NLR family pyrin domain containing 3 (NLRP3) inflammasome-dependent pyroptosis and pro-inflammatory responses were also activated as downstream pathways, contributing to myocardial hypertrophy." (PMID 40497954, 2025). "But overall, exploring the relationship between autophagy and NLRP3 inflammatory may provide new ideas for the treatment and prognosis of cardiac hypertrophy." (PMID 38172711, 2024). "Recently, NLRP3 inflammasome activation in cardiomyocytes has received increasing attention because its inhibition significantly attenuates pressure overload‐induced cardiac hypertrophy, fibrosis, and cardiac dysfunction." (PMID 39604027, 2024). "Our evidences suggested that impaired mitophagy may be a cause of cardiac hypertrophy induced by pressure overload, and semaglutide ameliorated the cardiac hypertrophy by improving mitophagy to suppress the activation of NLRP3 inflammasome." (PMID 38782946, 2024). "And the mechanism of miR-26a-5p and NLRP3 inflammasome aggravating pathological cardiac hypertrophy remain unclear." (PMID 38172711, 2024). "Targeting the expression of miR-26a-5p, as well as inhibiting the activation of autophagy and the NLRP3 inflammasome pathway, could offer additional treatments for pathological cardiac hypertrophy." (PMID 38172711, 2024). "Silica nanoparticles lead to cardiac hypertrophy and pyroptosis by the NLRP3/ROS/caspase-1 pathway." (PMID 38730417, 2024).
cardiac hypertrophy (continued). "Furthermore, real‐time PCR results suggested that NLRP3 deletion suppressed the expression of cardiac hypertrophy‐related genes (ANP, BNP, and Myh7) and cardiac fibrosis‐related genes (Col1a1 and CTGF) in obese hearts." (PMID 39604027, 2024). "Thus, pyroptosis serves a pathological role in cardiac hypertrophy, andinhibition of NLRP3 inflammatory vesicles is a potential target for treatingcardiac hypertrophy." (PMID 39484135, 2024). "On the other hand, TNF-α, a pro-inflammatory cytokine known to induce cardiac hypertrophy, fibrosis, dysfunction under pressure overload, and chronic heart injuries, may trigger the activation of NLRP3 through the elevation of ROS levels." (PMID 37958859, 2023). "Therefore, despite extensive research, further understanding is needed to determine the exact role of NLRP3 and confirm when and via which mechanism it is beneficial or detrimental in cardiac remodeling during hypertrophy." (PMID 37336361, 2023). "The findings of the present study indicate that chronic Ang II stimulation could activate cardiac oxidative damage and NLRP3 inflammasome-mediated inflammation, leading to cardiac hypertrophy and dysfunction, accompanied by MHRT inhibition." (PMID 36978920, 2023). "In addition, NLRP3 inflammasome is involved in pathological processes leading to HF, such as cardiac hypertrophy and fibrosis." (PMID 35647084, 2022). "Under pressure overload, S-nitrosylation of muscle LIM protein (MLP) increased the complex formation between toll-like receptor 3 (TLR3) and receptor-interacting protein kinase 3 (RIP3), inducing NLRP3 inflammasome activation, and promoting the development of myocardial hypertrophy." (PMID 35509275, 2022). "Meanwhile, silica nanoparticles (SiNPs) exposure is correlated with adverse cardiovascular effects, literature suggested SiNPs could trigger pyroptosis and cardiac hypertrophy via ROS/NLRP3/Caspase-1 signaling pathway." (PMID 35509275, 2022). "MCC950 could significantly decrease pressure overload-induced VA vulnerability by reversing HF-induced cardiac hypertrophy, fibrosis, electrical remodeling, and ion channel remodeling via inhibition of the NLRP3 inflammasome." (PMID 35287557, 2022). "Moreover, we also confirmed that the pressure overload-induced pyroptosis is driven by the NLRP3 inflammasome, and inhibiting the pyroptotic cascade alleviates cardiac hypertrophy." (PMID 33723236, 2021). "Notably, suppressing IL-1β and NLRP3 inflammasome pathways ameliorates TAC -induced ventricular hypertrophy in mice." (PMID 34168567, 2021). "Several studies have suggested that modulating inflammasome activity can reduce myocardial hypertrophy and fibrosis, and it has been observed that people with a lower ejection fraction have a greater presence of cardiac neutrophils and a higher activity range of NLRP3." (PMID 40564905, 2025). "In the present study, we found that cardiac mitophagy dysfunction induced by pressure overload can activate NLRP3 inflammasome, and lead to cardiac hypertrophy, and improving mitophagy by semaglutide could suppress the activation of NLRP3 inflammasome to alleviate cardiac hypertrophy." (PMID 38782946, 2024). "In present study, we find that dysfunction of mitophagy may play an important role in pressure overload-induced cardiac hypertrophy, and semaglutide ameliorates this type of cardiac hypertrophy by improving mitophagy to suppress the activation of NLRP3 inflammasome." (PMID 38782946, 2024). "However, NLRP3 is downregulated in myocardial remodeling induced by pressure load of aortic ligation, and NLRP3 knockout can downregulate inflammation signaling pathway, and aggravate cardiac hypertrophy, fibrosis, and inflammatory reaction." (PMID 37249295, 2023). "Moreover, NLRP3 inflammasome‐mediated pyroptosis contributes to cardiac hypertrophy induced by aortic constriction, and the inhibitor of NLRP3 inflammasome irisin can attenuate cardiac hypertrophy by inhibiting pyroptosis." (PMID 37125240, 2023).